TM4SF1 (transmembrane 4 L six family member 1)
Diseases named in the same sentence as TM4SF1 in open-access papers (continued):
Sharing a sentence is not in itself a finding about the gene and the disease.
bladder cancer (13 papers, 2019 to 2026). "In bladder cancer, TM4SF1 deficiency significantly upregulated PPARγ and forkhead transcription factor 3a (FOXO3a) and downregulated SIRT1 protein expression, forming a feedback loop that modulates the cell cycle." (PMID 33015133, 2020). "Finally, our discovery that most HV tumors exhibit enriched expression of TM4SF1, a gene that encodes a surface protein that has already been implicated in the pathogenesis of aggressive bladder cancers and other cancer cell types, has therapeutic implications." (PMID 40527915, 2025). "In bladder cancer, the transmembrane-4 L-six family member-1 (TM4SF1)-positive cancer subpopulation represents a paradigmatic example of how epigenetic plasticity contributes to MRD persistence." (PMID 41567490, 2026). "We tested both CAR T candidates against six bladder cancer cell lines with variable levels of endogenous TM4SF1 mRNA expression and surface protein expression." (PMID 40527915, 2025). "Our preclinical testing of TM4SF1-CAR T cells thus lays a foundation for future clinical trials in bladder cancer and other tumor types expressing TM4SF1." (PMID 40527915, 2025). "We detected a cancer cell state (Cluster 13) with clinical and mechanistic significance and found enriched expression of a targetable protein (TM4SF1) in HV bladder cancers." (PMID 40527915, 2025). "Chimeric antigen receptor (CAR) T cells engineered against TM4SF1 protein demonstrated in vitro and in vivo activity against bladder cancer cell lines in a TM4SF1 expression-dependent manner, highlighting its potential as a therapeutic target." (PMID 40527915, 2025). "Whereas the TM4SF1-CAR T cells exhibited anti-tumor activity against bladder cancer lines expressing TM4SF1 (including UMUC3, T24, 5637, 253JBV and UMUC1), the TM4SF1-CAR T cells did not kill HT1376, which is negative for TM4SF1." (PMID 40527915, 2025). "Immunohistochemical staining revealed that SCD, SUMF2, and KDEL2R were significantly more expressed in bladder cancer tissues compared to paracancerous tissues, while TM4SF1 exhibited higher expression in paracancerous tissues than in tumor tissues." (PMID 39104534, 2024). "Several studies have demonstrated that TM4SF1 overexpression positively correlates with tumor grade and can increase the migration and invasion of tumor cells, including ovarian cancer, bladder cancer, and pancreatic cancer." (PMID 38206300, 2024). "Transmembrane 4 L6 family member 1 (TM4SF1) is a tetraspannin that is highly expressed in a range of epithelial cancers including pancreatic, liver, lung, oesophageal breast and bladder cancers." (PMID 36831514, 2023). "TM4SF1 is upregulated in several epithelial cancers, including bladder cancer, and promotes the proliferation, migration and invasion of cancer cells by inducing EMT and cancer stemness." (PMID 34944855, 2021). "Studies have confirmed that TM4SF1 is highly expressed in various epithelial cancer cells, including pancreatic, liver, lung and bladder cancers." (PMID 33153498, 2020). "Similar results were also observed after silencing FASN or TM4SF1 in bladder cancer cells." (PMID 35480865, 2022). "Moreover, TM4SF1 promoted the proliferation and growth of human bladder cancer cells in vitro and in vivo and inhibited apoptosis by decreasing the ratio of Bax/B-cell lymphoma xl (Bcl-xl)." (PMID 33015133, 2020). "Taken together, these data demonstrate that TM4SF1 may be a new therapeutic target for TM4SF1-expressing bladder cancers, including tumors with variant histology and those lacking NECTIN4 expression, and can be successfully targeted using CAR T cell therapy in a mouse xenograft model." (PMID 40527915, 2025). "In an in vitro experiment, we demonstrated that TM4SF1, FASN, and IMPDH1 were elevated in some bladder cancer cell lines." (PMID 35480865, 2022). "A recent study suggested that TM4SF1 can regulate apoptosis and the cell cycle via the PARγ-SIRT1 feedback loop in bladder cancer cells." (PMID 33153498, 2020).
bladder cancer (continued). "Interestingly, the TM4SF1, ANXA1 and LOX genes have been identified in a fibroblast cluster for good prognosis in bladder cancer and are seen as therapeutic targets for fibrosis." (PMID 40271554, 2025). "TM4SF1 was highly expressed in the majority of tumor types namely, Cholangio carcinoma (CHOL), LIHC, THCA, Esophageal carcinoma (ESCA), and markedly lowly expressed in bladder cancer (BLCA), Kidney renal papillary cell carcinoma (KIRP)." (PMID 38206300, 2024). "TM4SF1 is a promising target because its expression is not limited to HV bladder cancers and its negative association with PVRL4/PRR4 expression suggests that targeted therapy against TM4SF1 could complement existing targeted agents." (PMID 40527915, 2025).
hepatocellular carcinoma (10 papers, 2016 to 2026). A malignant tumor that arises from hepatocytes. "Among its members, TM4SF1 and TM4SF5 are frequently overexpressed in various tumors, including hepatocellular carcinoma (HCC) and prostate cancer, where they promote EMT-associated signaling and are regarded as important therapeutic targets 21-23." (PMID 41356204, 2026). "Previous studies have demonstrated that TM4SF1 exerts an anti-apoptotic effect on cells, such as human hepatoma HepG2 cells and human gastric cancer cells." (PMID 37603094, 2023). "The expression levels of TM4SF1 were elevated in hepatocellular carcinoma (HCC) and were induced by Kras signalling." (PMID 31876386, 2021). "Therefore, we believe that MYH9 can act as the downstream molecule of TM4SF1 in hepatocellular carcinoma cells and be subject to unilateral positive regulation from TM4SF1." (PMID 37069693, 2023). "A recent study suggested that TM4SF1 could promote migration and metastasis by positively regulating the Wnt/β-catenin signalling in hepatocellular carcinoma." (PMID 33153498, 2020). "Although some achievements have been made in the study of TM4SF1, the effect of TM4SF1 on cancer stemness in hepatocellular carcinoma (HCC) and its molecular basis are yet to be reported." (PMID 37069693, 2023). "The expression of either TM4SF1 or TM4SF5 is enhanced compared with normal tissues in many different types of cancer, including hepatocellular carcinoma." (PMID 28129652, 2017). "TM4SF1 and TM4SF5 play roles in both cell proliferation leading to hepatocellular carcinoma and migration and invasion in cancer metastasis." (PMID 28129652, 2017). "Our previous studies showed that 86% of patients with hepatitis B virus-related hepatocellular carcinoma have overexpressed TM4SF1 in their liver cancer cells, but that adjacent normal tissues and normal liver tissues had no measureable expression of TM4SF1." (PMID 27153056, 2016). "We cultured five hepatoma cell lines (Hep3B, HepG2, LM3, Huh7, and MHCC97H) and normal liver cells LO2, extracted RNA and protein from the cells, and detected the expression of TM4SF1 at the RNA and protein levels using qPCR and Western blot (WB), respectively." (PMID 37069693, 2023).
colon cancer (9 papers, 2007 to 2024). "A recent study showed that TM4SF1 promoted proliferation, invasion, metastasis, and stemness in colon cancer." (PMID 37069693, 2023). "miR-552 promotes the migration of colon cancer cells by targeting ADAM28 and miR-9 inhibits colon cancer cell migration and invasion by downregulating TM4SF1." (PMID 28725241, 2017). "For example, miR-206 inhibits PGE2-induced proliferation and metastasis of colon cancer cells by targeting the transmembrane 4 L six family member 1 (TM4SF1) protein, while miR-128,89 miR-146a,90 miR-101,91 and miR-14392 can inhibit tumor progression by decreasing COX-2." (PMID 32561709, 2020). "Furthermore, we discovered that miR-206 directly regulates TM4SF1, which functioned as a metastasis suppressor of miRNA in various cancers, including breast, lung, glioblastoma, and colon cancers, by binding the predicted seed sites." (PMID 30135139, 2018). "From the data of GEO, the TM4SF1 gene, which is believed to be involved in cancer invasion and metastasis was also up-regulated in smokers, and metastatic form of colon cancer patients compared to primary form of colon cancer patients." (PMID 18034892, 2007).
gastric cancer (9 papers, 2009 to 2023). A primary or metastatic malignant neoplasm involving the stomach. "TM4SF1 is associated with diseases, such as non-small cell lung cancer and gastric cancer." (PMID 36685840, 2022). "However, the low expression of TM4SF1 has been found to be associated with carcinogenesis and development, tumor progression, and invasion of gastric cancer, which indicates TM4SF1 is a tumor suppressor for gastric cancer and a novel prognostic marker for patients with gastric cancer." (PMID 35153775, 2022). "Low expression of TM4SF1 is associated with carcinogenesis and development, tumor progression and invasion of gastric cancer, and poor overall survival of patients with GC." (PMID 29665316, 2018). "TM4SF1, also named OCTM4, belongs to the transmembrane 4L six superfamily and is associated with gastric carcinoma." (PMID 34439758, 2021). "In human gastric cancer, TM4SF1 increased cell proliferation and inhibited apoptosis by increasing Bcl2 expression and decreasing Bax expression." (PMID 33015133, 2020). "TM4SF1 also positively regulated the invasion and migration of human gastric cancer cells." (PMID 33015133, 2020). "Our data indicated TM4SF1 as a tumor suppressor gene was associated with carcinogenesis and development, tumor progression and invasion of gastric cancer, and poor overall survival of patients with GC and was an independent predictor for prognosis of patients with GC." (PMID 29665316, 2018). "The aim of this study was to investigate the clinical significance of TM4SF1 expression in gastric carcinoma (GC) tissues using 152 GC tissue samples and matched adjacent nontumor tissue samples analyzed by immunohistochemistry, and 13 fresh GC tissue samples analyzed by Western blotting." (PMID 29665316, 2018). "However, TM4SF1 also can be downregulated in gastric cancer and mammary ductal carcinoma in situ." (PMID 35153775, 2022). "In this study, we found that TM4SF1 protein levels were lower in gastric cancer tissues than gastric noncanerous tissues." (PMID 29665316, 2018). "TM4SF1 protein levels were lower in gastric cancer tissues than gastric noncanerous tissues." (PMID 29665316, 2018). "TM4SF1 levels were lower in gastric cancer tissues than gastric noncancerous tissues." (PMID 29665316, 2018). "However, the role of TM4SF1 in gastric cancer has not been elucidated." (PMID 29665316, 2018).
liver cancer (9 papers, 2009 to 2024). An epithelial or non-epithelial malignant neoplasm that arises from the liver. "The results showed that upregulation of TM4SF1 inhibited the autophagy of liver cancer cells and increased the susceptibility to tumorigenesis, and that downregulation of TM4SF1 markedly promoted the autophagy of cancer cells and decreased the susceptibility to tumorigenesis." (PMID 27153056, 2016). "Considering 374 patients with liver cancer in the TCGA database as the samples, we enriched many TM4SF1-related pathways." (PMID 37069693, 2023). "We verified the high expression of TM4SF1 in tumor spheres via the PCR experiment using the RNA extracted from the tumor spheres of liver cancer provided by the Cancer Research Institute of Southern Medical University, Guangzhou, China." (PMID 37069693, 2023). "We also measured the expression of TM4SF1 in all liver cancer cell lines using the TCGA database, and the results revealed that the majority of these cell lines had high levels of TM4SF1 expression." (PMID 37069693, 2023). "Since TM4SF1 is strongly expressed in liver cancer cells and tissues compared to normal liver cells and tissues, we investigated its impact on the stemness of HCC in this work." (PMID 37069693, 2023). "In liver cancer cells, TM4SF1 promoted growth and inhibited apoptosis; overexpression of TM4SF1 reduced apoptosis in vitro and increased proliferation in vivo, while decreased expression had the opposite effects." (PMID 33015133, 2020). "TM4SF1 is increased in epithelial cancer cells and regulates cell motility and invasion in colorectal and liver cancers." (PMID 30135139, 2018). "Silencing of TM4SF1 showed increased apoptosis and reduced cell migration in human liver cancer cells and the overexpression of TM4SF1 increased tumor growth and metastasis in vivo." (PMID 30135139, 2018). "Taken together, our results showed that overexpression of TM4SF1 significantly increased the proliferation and tumorigenesis of liver cancer cells." (PMID 27153056, 2016). "It should be noted that TM4SF1 is highly expressed in liver cancer, and liver cancer patients with TM4SF1 overexpression have worse five-year survival rates than those with low TM4SF1 expression, supporting our results." (PMID 27153056, 2016). "This suggests that in the pathogenesis of liver cancer, TM4SF1 upregulates cyclin D1 and PCNA and thereby promotes the growth, proliferation, and invasion of cancer cells." (PMID 27153056, 2016). "Autophagy can inhibit tumorigenesis, and increasing TM4SF1 expression reduces the number of autophagosomes that could inhibit liver cancer cell autophagy, thus promoting tumorigenesis." (PMID 33015133, 2020). "Thus, the purpose of the present study was to examine the role of TM4SF1 in regulating the proliferation, migration, and invasion of liver cancer cells." (PMID 27153056, 2016). "Our previous studies showed that TM4SF1 is highly expressed in liver cancer." (PMID 27153056, 2016). "To determine the molecular mechanism of how TM4SF1 promotes liver tumor growth and progression, we focused on several cancer-related proteins, which are known to play a major role in the development and progression of liver cancer." (PMID 27153056, 2016). "However, few studies have investigated the role of TM4SF1 in liver cancer." (PMID 27153056, 2016). "Thus, we speculate that in the early pathogenesis of liver cancer, TM4SF1 has a central role in the inhibition of apoptosis and autophagy that is mediated through its effects on caspase-3 and caspase-9." (PMID 27153056, 2016). "Thus, we speculate that in the early phase of liver cancer, downregulation of TM4SF1 plays an important role in the promotion of tumorigenesis." (PMID 27153056, 2016). "In order to explore the specific regulatory relationship between TM4SF1 and MYH9 in liver cancer cells, we silenced TM4SF1 and MYH9 respectively, and observed the expression of another molecule by WB experiment." (PMID 37069693, 2023).
liver cancer (continued). "Thus, we speculate that TM4SF1 upregulation inhibits apoptosis and induces abnormal proliferation of liver cancer cells by downregulating caspase-3 and caspase-9, and that this leads to the onset and progression of liver cancer." (PMID 27153056, 2016).
ovarian carcinoma (8 papers, 2019 to 2026). A malignant neoplasm originating from the surface ovarian epithelium. "Because TM4SF1 has selective expression features in tumors, can mediate tumor cell growth and invasion, as well as metastasis, and is closely associated with anti-tumor immune responses, TM4SF1 is a potential target for anti-invasion and metastasis in ovarian cancer." (PMID 30876464, 2019). "Positive TM4SF1 protein expression (100%) was observed in epithelial ovarian cancer tissues from FIGO stage III-IV patients, which was higher than that in tissues from FIGO stage I-II patients (76.2%) (P = 0.012)." (PMID 30876464, 2019). "The positive expression rates of TM4SF1 protein in epithelial ovarian cancer tissues, ovarian benign tumor tissues, and normal ovarian epithelial tissues were 90.9, 65.2, and 31.3%, respectively, and all the differences were significant (P < 0.05)." (PMID 30876464, 2019). "Our group performed immunohistochemistry and showed that the positive expression rate of TM4SF1 protein in epithelial ovarian cancer tissues was higher than that in benign ovarian tumor tissues and normal ovarian tissues." (PMID 30876464, 2019). "The results in this study showed that TM4SF1 protein expression in epithelial ovarian cancer at the late stage was higher than that at the early stage." (PMID 30876464, 2019). "The expression of TM4SF1 in normal ovarian epithelial tissues, benign ovarian tumor tissues, primary foci of epithelial ovarian cancer and the matched lymph mode metastatic foci was detected using immunohistochemistry to analyze its association with prognosis." (PMID 30876464, 2019). "Overexpression of TM4SF1 significantly enhanced the invasion and migration of human prostate cancer cells whereas silencing of TM4SF1 suppressed the migration and invasion of ovarian cancer cells." (PMID 33015133, 2020). "TM4SF1 is a potential target for anti-invasion and metastasis in ovarian cancer." (PMID 30876464, 2019). "A comparison of endothelial cells between healthy ovarian and ovarian cancer tissues revealed that genes such as RACK1, S100A6, and C1orf186 were significantly upregulated, while GMB2L1, TM4SF1, and EIF1 were significantly downregulated in the ovarian cancer samples." (PMID 37124501, 2023). "Univariate and multivariate analysis results showed that the FIGO stage and histological grade were both influencing factors of ovarian cancer patient prognosis, and positive TM4SF1 protein expression was not an independent factor affecting the prognosis of ovarian cancer patients (P > 0.05)." (PMID 30876464, 2019). "However, the results of multivariate analyses showed that the positive expression rate of TM4SF1 protein was not an independent prognostic factor for epithelial ovarian cancer patients." (PMID 30876464, 2019).
prostate carcinoma (7 papers, 2015 to 2020). A carcinoma that arises from epithelial cells of the prostate gland. "TM4SF1 location in the cytoplasm associated with the invasion of prostate cancer cells." (PMID 33015133, 2020). "Inhibition of TM4SF1 expression was shown to affect prostate cancer cell motility, which might be related to the loss of surface expression in prostate cancer cells." (PMID 33015133, 2020). "TM4SF1 expression was higher in aggressively metastatic prostate cancer cells than in indolent, androgen-sensitive cancer cells." (PMID 33015133, 2020). "Down-regulation of TM4SF1 gene expression using RNA interference technology can reduce the migration of prostate cancer cells and the metastasis ability of cervical cancer cells." (PMID 30876464, 2019). "Treatment with bicalutamide or 5-alpha-reductase downregulated the expression of TM4SF1 in prostate cancer cells, suggesting that TM4SF1 could be used to guide clinical treatment." (PMID 33015133, 2020). "A recent study showed that hsa-miR-141 can effectively interfere with TM4SF1 expression in prostate cancer to inhibit prostate cancer cell invasion and metastasis, which describes a new carcinogenesis mechanism of TM4SF1 and suggests the potential of targeting TM4SF1 in gene therapy." (PMID 30876464, 2019). "One study showed that overexpression of TM4SF1 markedly increased EMT and enhanced the invasion and migration of human prostate cancer cells." (PMID 33015133, 2020). "TM4SF1 could also significantly activate the extracellular regulated protein kinases extracellular signal-regulated kinase (ERK1/2) signaling pathway to increase the proliferation of DU145 cells and increase EMT in human prostate cancer." (PMID 33015133, 2020).